AMH (anti-Mullerian hormone)
Description:
The anti-Muellerian hormone (AMH) plays an important role in several reproductive functions. Anti-Muellerian hormone binds and activates AMHR2, its specific type-II receptor, that heterodimerizes with type-I receptors (ACVR1 and BMPR1A) to regulate target gene expression through downstream SMAD protein signal transduction. Produced and secreted by Sertoli cells of the male fetus, anti-Muellerian hormone induces Muellerian duct regression during male fetal sexual differentiation. In female, it is produced by granulosa cells of the preantral and small antral follicles and acts as a negative regulator of the primordial to primary follicle transition and decreases FSH sensitivity of growing follicles. Also plays a role in Leydig cell differentiation and function (By similarity).
Synonyms: MIS; MIF
Tractability: Antibody: UniProt places it where antibodies can reach, with high confidence; its Gene Ontology location is reachable by antibodies, with high confidence; UniProt predicts a signal peptide or a membrane-spanning region.
Gene: Protein-coding gene on chromosome 19 (2,249,309 to 2,252,073, forward strand). Ensembl gene ENSG00000104899.
Subcellular location: Secreted
Subcellular location (Human Protein Atlas): Aggresome; Vesicles; Predicted to be secreted
Pathways (Reactome):
Developmental Biology: Transcriptional regulation of testis differentiation
Signal Transduction: Signaling by BMP
Gene Ontology:
Molecular function: protein binding; signaling receptor binding; type II transforming growth factor beta receptor binding; hormone activity; transforming growth factor beta receptor binding; growth factor activity
Biological process: anti-Mullerian hormone receptor signaling pathway; Mullerian duct regression; positive regulation of gene expression; positive regulation of SMAD protein signal transduction; cell-cell signaling; development of primary male sexual characteristics; gonad development; Leydig cell differentiation; negative regulation of ovarian follicle development; ovarian follicle development; sex determination; sex differentiation; preantral ovarian follicle growth; response to xenobiotic stimulus
Cellular component: extracellular region; serine/threonine protein kinase complex
Genetic constraint (gnomAD): Loss-of-function variants: 40 observed, 23.55 expected, observed/expected ratio (o/e) 1.7, 90% interval 1.3 to 1.95. The synonymous counts are far from expectation, so gnomAD's model fits this gene poorly and the ratio says little. Missense variants: 1,019 observed, 614.29 expected, observed/expected ratio (o/e) 1.66, 90% interval 1.58 to 1.75. Synonymous variants: 536 observed, 314.29 expected, observed/expected ratio (o/e) 1.71, 90% interval 1.59 to 1.83.
Homologues: Orthologues: chimpanzee AMH (99% identical), macaque AMH (94% identical), pig AMH (76% identical), dog AMH (76% identical), guinea pig AMH (74% identical), mouse Amh (72% identical), rat Amh (72% identical), tropical clawed frog amh (30% identical), zebrafish amh (20% identical).
Diseases named in the same sentence as AMH in open-access papers:
AMH is named in the same sentence as 249 diseases in open-access papers, as found by Europe PMC text mining. Sharing a sentence is not in itself a finding about the gene and the disease. The quoted sentences say what the papers report.
Infertility (439 papers, 2010 to 2026). "Association among hysteroscopy, age, BMI, AMH, infertility years, good embryo, and clinical pregnancy (multivariable binary logistic regression analysis)." (PMID 41312455, 2025). "BMI, type of infertility, duration of infertility, causes of infertility, AMH, and a range of metabolic indicators were comparable between the two groups." (PMID 41019558, 2025). "A growing body of evidence indicates that serum AMH concentrations are significantly and positively associated with antral follicle count (AFC), while reduced AMH levels are linked to lower clinical pregnancy rates among infertile women." (PMID 41387944, 2025). "Polycystic Ovary Syndrome (PCOS), the leading cause of infertility worldwide, is characterised by oligo-anovulation, hyperandrogenism, polycystic ovarian morphology and high Anti-Müllerian hormone (AMH) levels, associated with severe metabolic disturbances." (PMID 40252252, 2025). "Endometriosis is linked with infertility; however, the exact impact of endometriosis and endometriosis surgery on AMH levels is less clear." (PMID 40507534, 2025). "A recent retrospective study confirmed that, for patients with endometriosis-related infertility, a low preoperative AMH value was negatively associated with chances of conception after laparoscopic surgery; however, it did not affect livebirth rates." (PMID 40507534, 2025). "Hypogonadism and undescended testes are associated with low AMH levels, suggesting a potential role of AMH in testicular descent; both traits are generally associated with infertility." (PMID 39032500, 2024). "Various variables were assessed in these patients after IVF, including age, BMI, duration of infertility, cause of infertility, AMH and FSH levels, number of ETs, and number of transferred embryos." (PMID 38651066, 2024). "The most common complication of PMDS is infertility, with reports of less than 20 % of patients with AMH or AMHR2 mutations having successfully reproduced." (PMID 39368309, 2024). "Women with male‐cause infertility, polycystic ovarian syndrome, low AMH levels, and women with unexplained infertility were all included in the research and underwent IVF." (PMID 39554321, 2024). "For patients’ characteristics, maternal age at oocyte retrieval, basal FSH, AFC, AMH, cause of infertility were significantly different (P<0.05) in three groups." (PMID 37772083, 2023). "A multiple regression model was used to assess the association between serum AMH, and other factors related to demographics and other aspects of infertile women with basal AFC." (PMID 38077683, 2023). "When adjusted by age, basal TSH, AMH, E2, endometrial thickness, type and causes of infertility, and transferred embryos, the dose-dependent relationships between D14 TSH and clinical pregnancy and live birth were observed." (PMID 37268813, 2023). "Basic and cycle characteristics, including age, AMH, BMI, ET, duration of infertility, quality of the transferred embryo, and cause of infertility, were comparable in both groups (positive and negative clinical pregnancy." (PMID 37122892, 2023). "Curve-fitting analysis indicated a curvilinear relationship between female age and clinical pregnancy rate in both groups, even after adjusting for male age, AMH level, number of cycles, causes of infertility, and COS protocol used." (PMID 38348053, 2023). "In infertile men, low serum AMH is associated with severely impaired gonadal function illustrated by poor semen quality and lower testosterone/LH ratio." (PMID 36855109, 2023). "In women with multiple deliveries, the history of ectopic pregnancy and causes of infertility were different among groups, the history of ectopic pregnancy is more frequent in women with low AMH levels." (PMID 36896183, 2023). "We conducted a binary logistic regression analysis, adjusting for factors such as couple ages, AMH level, number of cycles, causes of infertility, COS protocol used, fertilization methods, and type and duration of infertility." (PMID 38348053, 2023).
Infertility (continued). "Among the patients in the D ≤ 9 group, age, BMI, initial AMH level, and cause of infertility, as well as the oestradiol level on D8 of the stimulation, were not predictive of the chances of a live birth." (PMID 35566454, 2022). "This study was done on 100 infertile women to compare the association of AMH and other biochemical parameters with age and AFC." (PMID 36128562, 2022). "Among them, age, AMH levels, and causes of infertility are commonly used as predictors of IVF success." (PMID 35566454, 2022). "Significant differences were observed between the two groups in age, BMI, AMH, type of infertility, duration of infertility, cause of infertility, basal FSH, type of fertilization." (PMID 36522703, 2022). "This is because the models to be constructed essentially have a high degree of nonlinearity and the input of the model contains both continuous features (e.g., AFC, AMH, and bFSH) and discretized features (e.g., infertility type and infertility cause)." (PMID 35204580, 2022). "Prior research has found that psychological stress was negatively associated with serum AMH in infertile women." (PMID 35627519, 2022). "In conclusion, our data reveal an obvious positive association between serum T and AMH levels in infertile women." (PMID 33737663, 2021). "Consistently, DHEA-S quartile categories were positively associated with serum AMH levels in infertile women after adjustment for potential confounders." (PMID 33803980, 2021). "A total of 314 women with infertility due to various causes (172 individuals with AMH ≥1.1 ng/ml and 142 individuals with AMH > 1.1 ng/ml) were enrolled in this study." (PMID 34598733, 2021). "We found that there was a weak positive association between serum DHEA-S and AMH levels in infertile women (r = 0.190, p < 0.001)." (PMID 33803980, 2021). "In this large retrospective cross-sectional study of 1935 infertile women, higher serum T concentrations were associated with higher serum AMH levels after adjustment for potential confounders." (PMID 33737663, 2021). "Risk factors were cause of infertility, age, BMI, AMH, the number of oocytes retrieved, rLH supplementation, and BMI among others." (PMID 35111134, 2021). "In conclusion, our data demonstrated a positive association between serum DHEA-S and AMH levels in infertile women." (PMID 33803980, 2021). "Another study claims that normal FMR1 repeat length outside 26 > CGG > 34 concur with a higher XCI skew, a putative mechanism underlying the ovarian reserve impairment (as assessed by AMH), particularly in infertile older females." (PMID 33281866, 2020). "In our study, AMH was recorded in 287 infertile women, who were referred to a specialized infertility clinic and the results showed a median AMH level of 3.20 ng/ml, significantly associated with lower AFC levels." (PMID 32259002, 2020). "Current study was conducted to determine the association between level of anti-mullerian hormone (AMH) and the infertility treatment outcomes in infertile females with endometriosis versus the non-endometriosis infertile subject." (PMID 30775688, 2018). "Donation of ovum is prohibited in various countries; thus AMH is a relevant marker to screen women at a higher risk of developing chemotherapy induced infertility, referring them well in time for ART consultation and fertility preservations." (PMID 26977116, 2016). "In recent years, a new functional role for AMH in ovarian follicle development has been reported based on studies using Amh knockout mice; these animals display infertility associated with the early depletion of the follicle pool." (PMID 27414805, 2016). "Age of women, age of partner, and serum AMH level was related with the hope of women to have a child and association with sexual distress of infertile women." (PMID 28913070, 2015).
Infertility (continued). "Endometriosis is a well-known cause of infertility, and the anti-Mullerian hormone (AMH) is an accepted biomarker of ovarian reserve and response to artificial reproductive technology procedures." (PMID 26596960, 2015). "AMH was an independent risk factor for infertility in PCOS patients (OR = 1.058)." (PMID 41545945, 2026). "In model 1, after controlling for age, BMI, AMH, type of infertility and causes of infertility, MTHFR 677CT (adjusted OR, 1.225; 95% CI, 1.087–1.380) and TT (adjusted OR, 1.355; 95% CI, 1.110–1.654) were positively associated with the risk of vitamin D deficiency compared with CC." (PMID 41019558, 2025). "Research has shown that metformin may influence AMH levels, particularly in conditions such as polycystic ovary syndrome, a common cause of infertility, where AMH levels are typically elevated." (PMID 40281834, 2025). "Lower levels of AMH often correspond with diminished ovarian reserve, associated with reduced estradiol production, which can hinder follicular development and ovulation, contributing to infertility." (PMID 39336427, 2024). "One explanation for the discrepancy could be the heterogenous caused for male infertility and some infertile men may have higher serum AMH levels due to more immature Sertoli cells that would limit the clinical applicability of a “high” or “normal” serum AMH." (PMID 36855109, 2023). "We speculate that the elevated AMH associated with PCOS appears to skew the data when examining all patients with infertility." (PMID 37020210, 2023). "Explorative outcomes were associations between serum AMH and gonadal function in infertile men." (PMID 36855109, 2023). "However, initial AMH level, cause of infertility, and oestradiol levels on D8 of stimulation were similar in both groups." (PMID 35566454, 2022). "However, low AMH occurs on a spectrum and very low levels are a risk for miscarriage and infertility." (PMID 35566443, 2022). "Successful treatment with IUI was statistically significantly associated with lower female age, infertility due to anovulation or unknown female infertility reason, higher levels of AMH and TPMSC > 15 mil." (PMID 36069921, 2022). "This study aimed to investigate the association between serum T and AMH levels in infertile women." (PMID 33737663, 2021). "Therefore, we conducted a large cross-sectional study in infertile women to clarify the association between serum T and AMH concentrations." (PMID 33737663, 2021). "The discrepancies between studies could be attributed to methodological causes, such as different criteria to select infertile men or the use of different methods to assess AMH concentration." (PMID 32290279, 2020). "The decrease in AMH pretreatment might be caused by chronic inflammation and increased levels of cytokines, especially IL-6, which have been shown to be associated with the occurrence of EM-associated infertility." (PMID 38562412, 2024). "Moreover, only infertile men with the lowest AMH had severely impaired gonadal function, which indicates that low AMH in infertile men may be considered a risk factor for severely impaired gonadal function, but this may not be the case for fertile men." (PMID 36855109, 2023). "Therefore, these patients may be less likely to need banked embryos or oocytes to conceive in the future, though additional research is needed to better stratify risk of infertility and pre-treatment biomarkers such as AMH are being explored." (PMID 34315890, 2021). "Age and BMI influence AMH cut-offs, and higher AMH levels are associated with more severe PCOS phenotypes and increased infertility risk." (PMID 41545945, 2026). "At least 90% of the population, translating to approximately one in five women with infertility, show discordant AFCs and AMH levels." (PMID 40141728, 2025). "Prior to matching, significant differences were observed between the two groups with respect to age, type of infertility, AMH, AFC and basal FSH." (PMID 40055770, 2025).
Infertility (continued). "These adjustment factors included female age, female BMI, duration of infertility, female AMH, MII oocytes, male age, male BMI, seminal concentration, semen type, sperm extraction method, and bAFC." (PMID 39670421, 2025). "Conversely, the PGT group showed significantly lower duration of infertility (p < 0.001), AMH levels (p < 0.001), number of retrieved oocytes (p < 0.001), and metaphase II oocytes (p < 0.001), compared to the non-PGT group." (PMID 40448728, 2025). "There are statistical significant differences regarding hormone levels, testosterone, LH, and AMH between infertile women with RIF and the control group." (PMID 40218218, 2025). "Serum AMH levels in adult women are part of the diagnostic criteria for polycystic ovary syndrome (PCOS), a condition with marked infertility and metabolic risks." (PMID 40108611, 2025). "Despite age, the discordance between AMH levels and AFCs in infertile women can be attributed to multiple factors, such as body mass index, socioeconomic status, and environmental/nutritional factors, like vitamin D status." (PMID 40141728, 2025). "Women with pre-existing reproductive health disorders, such as PCOS and infertility, are more vulnerable to stress and are more likely to experience a decline in AMH level and, by extension, ovarian reserve following stressful experiences." (PMID 41196903, 2025). "This study revealed statistically significant differences in AMH levels between the endometriosis and tubal factor infertility groups." (PMID 39493123, 2024). "In this study, we enrolled 55 women aged between 18 and 42 years with an FSH value < 10 IU/mL, AMH value > 1 ng/mL, antral follicle count > 8, and BMI < 30 affected by different forms of infertility before and during the coronavirus pandemic." (PMID 39125969, 2024). "Our study with a large sample size showed the mean values of AMH to be significantly lower in infertile than fertile populations." (PMID 39446778, 2024). "The crude and adjusted ORs for infertility in women with low AMH was 0.71 (95% CI: 0.42–1.23) and 0.76 (95% CI: 0.44–1.33), respectively." (PMID 39340554, 2024). "Six clinical indicators, including female age, infertility type, duration of infertility, intraoperative diagnosis, ovulation monitoring, and anti-Müllerian hormone (AMH) level, were screened out." (PMID 39015183, 2024). "The postoperative AMH concentrations were 1.04 (IQR 0.89) ng/ml for patients with infertility and 0.31 (IQR 3.14) ng/ml for patients who became pregnant postoperatively, and the difference was not significant (p=0.885)." (PMID 38562412, 2024). "AMH levels < 0.7 ng/mL were observed in 26 (10%) women with unexplained infertility and 35 (14%) women with male infertility (p = 0.28)." (PMID 39340554, 2024). "Mean age of patients with infertility at time of diagnosis was 34 ± 5.8 years, and median AMH level was 1.08 (0.35–1.69) ng/ml." (PMID 38381389, 2024). "At time of follow-up, 69.9% (n = 40) regained regular menstrual cycles, 52.6% (n = 20) < 40 years showed a diminished ovarian reserve with AMH levels < 1.1 ng/ml and 28.3% (n = 15) suffered from infertility." (PMID 38381389, 2024). "Overall, IVIg and control groups were similar in terms of maternal age at index embryo transfer, anti-mullerian hormone (AMH) levels and factors contributing to infertility." (PMID 38365988, 2024). "In conclusion, several characteristics were found to be lower in patients with endometriosis, including AMH levels, the number of oocytes, and embryo cleavage rates compared with tubal factor infertility." (PMID 39493123, 2024). "The results showed that the age of patients, infertility factors, BMI, and AMH had effects on the live birth rate, and the difference was statistically significant (P<0.05)." (PMID 39006360, 2024). "For this latter threshold, the crude and adjusted ORs for infertility in women with low AMH were 0.45 (95% CI: 0.22–0.93) and 0.44 (95% CI:0.21–0.91), respectively." (PMID 39340554, 2024).